UBE2L3 (ubiquitin conjugating enzyme E2 L3)
Description:
Ubiquitin-conjugating enzyme E2 that specifically acts with HECT-type and RBR family E3 ubiquitin-protein ligases. Does not function with most RING-containing E3 ubiquitin-protein ligases because it lacks intrinsic E3-independent reactivity with lysine; in contrast, it has activity with the RBR family E3 enzymes, such as PRKN, RNF31 and ARIH1, that function like RING-HECT hybrids. Accepts ubiquitin from the E1 complex and catalyzes its covalent attachment to other proteins. Mediates ubiquitination by the CUL9-RBX1 complex. In vitro catalyzes 'Lys-11'-linked polyubiquitination. Involved in the selective degradation of short-lived and abnormal proteins. Down-regulated during the S-phase it is involved in progression through the cell cycle. Regulates nuclear hormone receptors transcriptional activity. May play a role in myelopoiesis.
Synonyms: UBCH7; E2-F1; L-UBC; UbcM4
Tractability: Small molecule: a structure with a bound ligand is known; it has a binding pocket of medium quality. PROTAC: UniProt records ubiquitination sites on it; ubiquitination databases record sites on it; its protein half-life has been measured.
Target class: Enzyme; Transferase
Gene: Protein-coding gene on chromosome 22 (21,549,447 to 21,624,034, forward strand). Ensembl gene ENSG00000185651.
Subcellular location: Nucleus; Cytoplasm
Subcellular location (Human Protein Atlas): Cytosol; Nucleoplasm; Primary cilium transition zone
Pathways (Reactome):
Metabolism of proteins: E3 ubiquitin ligases ubiquitinate target proteins; Synthesis of active ubiquitin: roles of E1 and E2 enzymes
Autophagy: PINK1-PRKN Mediated Mitophagy
Immune System: Antigen processing: Ubiquitination & Proteasome degradation
Programmed Cell Death: Regulation of necroptotic cell death
Signal Transduction: Regulation of TNFR1 signaling
Gene Ontology:
Molecular function: protein binding; RNA binding; transcription coactivator activity; ubiquitin conjugating enzyme activity; ubiquitin protein ligase binding; ubiquitin-protein transferase activator activity; ubiquitin-protein transferase activity; enzyme binding; ubiquitin-like protein transferase activity
Biological process: cell cycle phase transition; cell population proliferation; cellular response to glucocorticoid stimulus; cellular response to steroid hormone stimulus; positive regulation of establishment of protein localization to mitochondrion; positive regulation of protein ubiquitination; protein K11-linked ubiquitination; protein polyubiquitination; protein ubiquitination; regulation of DNA-templated transcription; protein modification process; ubiquitin-dependent protein catabolic process; positive regulation of DNA-templated transcription; protein modification by small protein conjugation
Cellular component: cytoplasm; nucleus; cytosol; nucleoplasm; ubiquitin ligase complex
Genetic constraint (gnomAD): Loss-of-function variants: 1 observed, 15.66 expected, observed/expected ratio (o/e) 0.0639, 90% interval 0.022 to 0.3. The synonymous counts are far from expectation, so gnomAD's model fits this gene poorly and the ratio says little. Missense variants: 39 observed, 178.13 expected, observed/expected ratio (o/e) 0.22, 90% interval 0.17 to 0.29. Synonymous variants: 41 observed, 62.79 expected, observed/expected ratio (o/e) 0.65, 90% interval 0.51 to 0.85.
Homologues: Orthologues: guinea pig UBE2L3 (100% identical), mouse Ube2l3 (100% identical), rat Ube2l3 (100% identical), zebrafish ube2l3a (95% identical), tropical clawed frog ube2l3 (93% identical), zebrafish ube2l3b (91% identical). Paralogues in human: UBE2L5 (97% identical), UBE2L6 (52% identical), UBE2D4 (38% identical), UBE2D1 (37% identical), UBE2D2 (36% identical), UBE2D3 (36% identical), UBE2E1 (33% identical), UBE2E2 (33% identical), UBE2E3 (33% identical), UBE2Q2 (22% identical), UBE2Q1 (21% identical), UBE2QL1 (20% identical).
Diseases named in the same sentence as UBE2L3 in open-access papers:
UBE2L3 is named in the same sentence as 63 diseases in open-access papers, as found by Europe PMC text mining. Sharing a sentence is not in itself a finding about the gene and the disease. The quoted sentences say what the papers report.
systemic lupus erythematosus (14 papers, 2015 to 2024). An autoimmune multi-organ disease typically associated with vasculopathy and autoantibody production. "There are several reports linking a single risk haplotype across the UBE2L3/UBCH7 gene with systemic lupus erythematosus and autoimmune diseases." (PMID 28446710, 2017). "GWAS of systemic lupus erythematosus identified rs140490 as the most strongly associated SNP, which is located downstream of the promoter region of UBE2L3." (PMID 27729585, 2016). "Also, SLE susceptibility SNPs of TNFAIP3 interact with those of UBE2L3, and these variations act synergistically to activate NF-κB, thereby increasing the risk of lupus." (PMID 38329126, 2024). "In a shared genetics study between IgAN and systemic lupus erythematosus (SLE), we previously observed variants of UBE2L3, a gene involved in ubiquitin/proteasome pathway, were associated with susceptibility to both autoimmune diseases." (PMID 32792854, 2020). "Notably, the risk allele rs5754217 shows significant association with systemic lupus erythematosus and rheumatoid arthritis, suggesting that both autoimmune rheumatological diseases may have UBE2L3 as a common susceptibility locus." (PMID 27729585, 2016). "Genetic variation in the UBE2L3 has been demonstrated in many autoimmune diseases such as systemic lupus erythematosus (SLE), rheumatoid arthritis (RA) and Crohn’s disease (CD)." (PMID 27094594, 2016). "Five independent studies reported increased expression of UBE2L3 from patients with lupus compared with healthy controls in different cell lines." (PMID 25880549, 2015). "By using data from a genome-wide association study of systemic lupus erythematosus (SLE), we observed a single risk haplotype spanning UBE2L3, consistently aligned across multiple autoimmune diseases, associated with increased UBE2L3 expression in B cells and monocytes." (PMID 25640675, 2015). "Intriguingly, studies also reported UBE2L3 plays a role in immune-related disease, UBE2L3 influence autoimmunity in patients with Systemic lupus erythematosus (SLE)." (PMID 38795139, 2024). "Moreover, analysis of B-cell subsets from human blood samples reveals that the UBE2L3 risk allele is specifically associated with increased levels of UBE2L3 in plasmablasts and plasma cells of systemic lupus erythematosus-affected patients, but not in healthy individuals." (PMID 27729585, 2016). "UBE2L3 is strongly associated with systemic lupus erythematosus (SLE) in genome-wide association studies and other genetic studies, as well as multiple autoimmune diseases.5–11 UBE2L3 is an E2 ubiquitin-conjugating enzyme, also known as UbcH7." (PMID 25640675, 2015). "Genes that were significant with at least two variables include: BTNL2 for alopecia areata, NOD2 for Crohn’s disease, PLA2R1 for membranous neuropathy, LMO1 for neuroblastoma, and TNPO3, UBE2L3, HLA-DRA, and HIC2 for systemic lupus erythematosus." (PMID 26170196, 2015).
autoimmune disease (11 papers, 2015 to 2022). A disorder resulting from loss of function or tissue destruction of an organ or multiple organs, arising from humoral or cellular immune responses of the individual to their own tissue constituents. "In genome-wide association studies (GWAS) and other genetic studies, UBE2L3 has been to be implicated in a variety of autoimmune diseases." (PMID 35265070, 2022). "A single haplotype spanning UBE2L3, rs140490, was associated with increased UBE2L3 expression in B cells and aligned across multiple autoimmune diseases." (PMID 28456914, 2017). "The ubiquitin conjugating enzyme E2L3 (UBE2L3) gene is associated with susceptibility to many autoimmune diseases." (PMID 27094594, 2016). "UBE2L3, an E2 ubiquitin-conjugating enzyme, was also highlighted in the Immunochip study as it has previously been implicated in other autoimmune diseases." (PMID 27388770, 2016). "UBE2L3 is associated with increased susceptibility to numerous autoimmune diseases, but the underlying mechanism is unexplained." (PMID 25640675, 2015). "Taken together, these data suggest that increased abundance of UBE2L3 and an up-regulated NF-κB response may play a causative role in abnormal B-cell differentiation and proliferation in autoimmune diseases." (PMID 27729585, 2016). "It is tempting to speculate that increased UBE2L3 expression and elevated UBE2L3 activity may be causative of altered immune response pathways triggering autoimmune diseases." (PMID 27729585, 2016). "Therefore, a higher expression and higher activity of UBE2L3 may be the cause of autoimmune diseases caused by altered immune response pathways." (PMID 35265070, 2022). "In addition, UBE2L3 was found to have increased expression in a number of other autoimmune diseases, including CD, T1D, SS, PS and PA, using the same database, indicating that UBE2L3 might be the key player in disease association of this region." (PMID 25880549, 2015). "Wang and his colleagues found that mutations in the ubiquitin-conjugating enzyme E2L3 (UBE2L3) gene may be related to the high risk of Hashimoto’s thyroiditis (HT) in Han Chinese, indicating that ubiquitination may be involved in thyroid-related autoimmune diseases." (PMID 36076300, 2022). "The E2 ubiquitin-conjugating enzyme UBE2L3 is a potential target for several autoimmune disorders." (PMID 35406655, 2022). "Taken as a whole, these results support the concept that by regulating basal and chronic low-level activation of NF-κB, the abundance of UBE2L3 might play a major regulatory role in abnormal B cell differentiation and proliferation in autoimmune diseases." (PMID 25640675, 2015). "Furthermore, the specific mechanism of UBE2L3 in autoimmune diseases needs to be studied further." (PMID 35265070, 2022). "Because UBE2L3 is highly abundant in plasmablasts and plasma cells, our study provides primary evidence that UBE2L3 could potentially be a therapeutic target in SLE and possibly for other autoimmune diseases or plasma cell diseases such as multiple myeloma." (PMID 25640675, 2015).
Crohn disease (8 papers, 2015 to 2024). A gastrointestinal disorder characterized by chronic inflammation involving all layers of the intestinal wall, noncaseating granulomas affecting the intestinal wall and regional lymph nodes, and transmural fibrosis. "In the original GWAS and in a combined analysis of two independent Dutch replication cohorts, two novel potential risk genes for Crohn’s disease were identified: UBE2L3 and BCL3." (PMID 35265070, 2022). "For example, rs5754426 is the top ranked variant among 92 SNPs in the locus—which includes some newly identified SNPs associated with celiac disease (UBE2L3 rs2298428), Crohn’s disease (CD) and psoriasis (YDJC rs181359), as well as chronic hepatitis B virus infection (UBE2L3 rs4821116)." (PMID 25786114, 2015). "Our analysis resulted in five candidate genes corresponding to two of the major IBD subtypes: UBE2L3 and SLC22A4 for Crohn’s Disease and TCF19, C6orf47 and SNAPC4 for Ulcerative Colitis." (PMID 34968289, 2020).
cervical cancer (6 papers, 2020 to 2024). A primary or metastatic malignant neoplasm involving the cervix. "HPV E7 was previously shown to be ubiquitinated and degraded by CUL1 and UBE2L3 in cervical cancer cells." (PMID 38226814, 2024). "The chromatin immunoprecipitation (ChIP) assay data showed that doxorubicin treatment promoted the binding of HP1γ to the promoter region of UBE2L3 gene in cervical cancer cells." (PMID 32825184, 2020).
cervical cancer (continued). "We next evaluated whether doxorubicin, which mediates the nuclear import of HP1γ and UBE2L3 suppression, can reverse cisplatin resistance in SiHa cells that showed the highest IC50 value of cisplatin among the three cervical cancer cell lines." (PMID 32825184, 2020). "Analysis of GEO profiles (GDS2416) in 33 different biopsies from 16 cervical cancer patients showed a negative correlation between the expression of UBE2L3 and CBX3 (a gene encoding HP1γ), whereas the expression of UBE2L3 and CBX1 (a gene encoding HP1β) showed a positive correlation." (PMID 32203172, 2020).
hepatocellular carcinoma (5 papers, 2020 to 2024). A malignant tumor that arises from hepatocytes. "UBE2L3 is one of the most abundant E2s in mammalian cell lines and associated with diverse cancers including hepatocellular carcinoma, oral cancer, prostate cancer, and non-small cell lung cancer." (PMID 32203172, 2020). "Finally, higher UBE2L3 mRNA levels have been associated with tumor size, clinical grade, and prognosis of hepatocellular carcinoma, but its depletion is related to proliferation inhibition and apoptosis induction." (PMID 35678668, 2022). "Furthermore, several studies have suggested that the depletion of UBE2L3 inhibits the proliferation and induces apoptosis of hepatocellular carcinoma cells." (PMID 38656363, 2024). "In liver cancer and oral squamous cell carcinoma, UBE2L3 was reported to be an important pro-tumorigenic factor in carcinogenesis and may be a potential treatment target for hepatocellular carcinoma." (PMID 35768832, 2022).
Parkinson disease (5 papers, 2016 to 2024). A progressive degenerative disorder of the central nervous system characterized by loss of dopamine producing neurons in the substantia nigra and the presence of Lewy bodies in the substantia nigra and locus coeruleus. "Studies on UBE2L3 have found that it has an abnormal expression in many diseases, mainly immune diseases, tumors and Parkinson’s disease." (PMID 35265070, 2022). "In Parkinson’s disease, a variation in the expression of the E2 enzyme, UBE2L3 (UbcH7), has been observed." (PMID 39596581, 2024).
psoriasis (5 papers, 2015 to 2025). An autoimmune condition characterized by red, well-delineated plaques with silvery scales that are usually on the extensor surfaces and scalp. "Common genetic variants such as FUT2, UBE2L3, CDKAL1, SH2B3 and apolipoprotein E are more frequently found in psoriasis patients, having multiple functions that would explain their dual role in susceptibility to psoriasis and MS." (PMID 40003621, 2025).
chronic hepatitis B (4 papers, 2015 to 2022). "UBE2L3 was associated recently with the GWAS of chronic hepatitis B in the Han community, showing that UBE2L3 is required for overcoming hepatitis B virus infections." (PMID 35265070, 2022). "A recent GWAS found that the UBE2L3 locus is associated with chronic hepatitis virus B infection in Han Chinese patients, suggesting that UBE2L3 is required to clear hepatitis virus B infections." (PMID 27729585, 2016).
lung adenocarcinoma (4 papers, 2023 to 2025). A carcinoma that arises from the lung and is characterized by the presence of malignant glandular epithelial cells. "In addition, UBE2L3 promotes lung adenocarcinoma invasion and metastasis." (PMID 38795139, 2024). "In addition, proteins such as ASS1, ITCH, or UBE2L3 involved in pathways related to the inhibition of a particular molecular background could be used as potential response biomarkers, thereby improving the efficacy of this therapeutic approach to combat lung adenocarcinoma." (PMID 37762133, 2023). "Additionally, UBE2L3 in promoting the migration and invasion of lung cancer cells, and can be used as a potential response biomarker to enhance the efficacy of HSP90 inhibitors against lung adenocarcinoma." (PMID 38656363, 2024).